C17orf75 (chromosome 17 open reading frame 75)
Description:
As component of the WDR11 complex acts together with TBC1D23 to facilitate the golgin-mediated capture of vesicles generated using AP-1. May have a role in spermatogenesis.
Synonyms: NJMU-R1; SRI2
Tractability: PROTAC: ubiquitination databases record sites on it; its protein half-life has been measured.
Gene: Protein-coding gene on chromosome 17 (32,324,565 to 32,350,023, reverse strand). Ensembl gene ENSG00000108666.
Subcellular location: Golgi apparatus, trans-Golgi network; Cytoplasmic vesicle
Subcellular location (Human Protein Atlas): Cytosol; Golgi apparatus
Gene Ontology:
Molecular function: protein binding
Biological process: intracellular protein transport
Cellular component: cytoplasmic vesicle; cytosol; trans-Golgi network; Golgi apparatus
Genetic constraint (gnomAD): Loss-of-function variants: 32 observed, 45.29 expected, observed/expected ratio (o/e) 0.71, 90% interval 0.53 to 0.95. The upper end of that interval is the gene's LOEUF score, 0.95, which puts it in group 4 of 6, group 1 being the genes least tolerant of losing a copy. Missense variants: 423 observed, 472.71 expected, observed/expected ratio (o/e) 0.89, 90% interval 0.83 to 0.97. Synonymous variants: 157 observed, 160.3 expected, observed/expected ratio (o/e) 0.98, 90% interval 0.86 to 1.12.
Homologues: Orthologues: chimpanzee C17H17orf75 (99% identical), macaque C16H17orf75 (96% identical), dog C17orf75 (93% identical), guinea pig C17orf75 (89% identical), mouse 5730455P16Rik (89% identical), rat C10h17orf75 (88% identical), rabbit C17orf75 (84% identical), pig C17orf75 (79% identical), tropical clawed frog c10h17orf75 (59% identical), zebrafish C3H17orf75 (49% identical).
Diseases named in the same sentence as C17orf75 in open-access papers:
C17orf75 is named in the same sentence as 4 diseases in open-access papers, as found by Europe PMC text mining. Sharing a sentence is not in itself a finding about the gene and the disease. The quoted sentences say what the papers report.
brain tumors (1 paper, 2022). "Further validation is needed to confirm the association of C17orf75 with pediatric brain tumors." (PMID 35545612, 2022).
C17orf75 also shares sentences with these, for which no sentence is quoted: breast carcinoma (1 paper); prostate carcinoma (1); testicular cancer (1).